AR (androgen receptor)
Diseases named in the same sentence as AR in open-access papers (continued):
Sharing a sentence is not in itself a finding about the gene and the disease.
prostate carcinoma (continued). "Since LCN2 could facilitate cell proliferation of castration-resistant prostate cancer via androgen receptor, LCN2 could be a novel target in cancer therapy." (PMID 35327169, 2022). "Improved understanding of AR-related networks may contribute to the discovery of new therapeutic targets for AR-related diseases, such as prostate cancer or AGA." (PMID 34983378, 2022). "AR may also indirectly accelerate DNA replication in prostate cancer cells through hyperphosphorylated RB." (PMID 36548336, 2022). "FAK can promote androgen-independent AR stimulation in prostate cancer." (PMID 35768871, 2022). "Depletion of AR activity halts the proliferation of prostate cancer cells." (PMID 35708495, 2022). "Although this contradiction may be influenced by the cancer stage or context, it provides opportunities for future studies to ascertain the molecules or intermediates in AR signaling that are modulated by SIRT1 in favor of the progression of prostate cancer." (PMID 36291902, 2022). "Pirh2 was shown to regulate the AR activity in prostate cancer cells both directly by recruiting the AR transcription factor to the ARE sequence located in the promoter region of the PSA-coding gene and, indirectly, by downregulating the chromatin repressor, histone deacetylase HDAC1." (PMID 35563824, 2022). "Suppresses AR signaling; reduces prostate cancer cell proliferation." (PMID 35547880, 2022). "As a result, AR-targeted therapies focusing on the N-terminal domain or DBD of AR have become a subject of intense interest as a potentially promising strategy to overcome AR heterogeneity in prostate cancer." (PMID 35864113, 2022). "In addition, using a tissue-specific transgenic model, we demonstrate that cell type specific protein synthesis is essential for the maintenance of tumor heterogeneity in both basal and intermediate cells in the context of AR-low prostate cancer." (PMID 36511483, 2022). "AR may also be activated by ligand-independent pathways (testosterone or dihydrotestosterone) observed in prostate cancer." (PMID 36361793, 2022). "Aerobic exercise may reduce prostate cancer progression and prostate cancer-specific death by influencing energy metabolism, inflammation, oxidative stress, and androgen receptor signalling pathways." (PMID 35063040, 2022). "In addition to HRD/DRD, several trials measured biomarkers related to other mechanisms in prostate cancer, including androgen receptor, ETS fusions, WNT, PI3K, and Cell cycle mechanisms." (PMID 36171797, 2022). "This landscape of AR cistrome can be pathologically reprogrammed in human prostate cancer." (PMID 34919781, 2022). "In other cancer forms, especially prostate cancer, AR has been shown to regulate numerous miRs." (PMID 35661403, 2022). "The analyses described herein are the largest report to date examining the impact of a broad range of androgen‐targeting therapies that included androgen receptor inhibitors and androgen synthesis inhibitors on neurodegenerative disease incidence in a cohort of men with prostate cancer." (PMID 35293700, 2022). "Metastatic prostate cancer can be present either at the time of diagnosis, termed hormone-sensitive (mHSPC), or following therapeutic resistance to androgen/androgen receptor (AR) pathway inhibitors, known as metastatic castration-resistant prostate cancer (mCRPC)." (PMID 35204808, 2022). "In addition to being a master regulator of the luminal cell secretory program, AR appears to be essential in the regulation of basal to luminal cell reprogramming with critical aberrant reprogramming in prostate cancer." (PMID 35203681, 2022).
prostate carcinoma (continued). "To investigate the underlying mechanisms of sexual dimorphism in the skeletal effects of Sirt1 haplo-insufficiency, we studied sex hormone receptors, as a cross talk between SIRT1 and ERα and AR has been previously reported in the context of breast and prostate cancer, respectively." (PMID 36568088, 2022). "Therefore, oncogenic AR action in prostate cancer development and progression needs to be understood for designing more effective therapies." (PMID 35902588, 2022). "Androgen receptor (AR) plays a pivotal role in prostate cancer (PCa) initiation and progression." (PMID 36408179, 2022). "In addition, silencing of EPHX2 has been proved to reduce tumor cell viability, induce apoptosis, and inhibit androgen receptor signaling in prostate cancer." (PMID 35236335, 2022). "AR is a transcription factor that plays a pivotal role in the development of prostate cancer." (PMID 35740507, 2022). "A recent study suggested that MLN could also suppress prostate cancer (PCa) cells specifically by shutting down the transcription of the androgen receptor (AR) and its downstream targets." (PMID 35354476, 2022). "Studying how the AR cistrome is transformed involves examining how the AR interacts with other key transcription factors in prostate cancer that can dictate its chromatin binding activity, as well as examining widespread chromatin alterations which can alter the AR cistrome more globally." (PMID 36212399, 2022). "Furthermore, although heterogenous subpopulations have been connected to prostate cancer (PCa) progression and AR therapy resistance, the key survival factor of lineage-plastic and stem-like cells has yet to be defined." (PMID 36065066, 2022). "knockdown of PABPC1 inhibited the proliferation of AR-positive prostate cancer cells." (PMID 36531055, 2022). "In addition, the molecular docking of PROTAC 5 with AR and the active site of DDB1-CRBN E3 ubiquitin ligase complex provided guidance to design new PROTAC degrons targeting AR for prostate cancer therapy." (PMID 35702041, 2022). "Furthermore, other upstream mediators of autophagy including ATG4B, ATG4D, ULK1 and ULK2 are regulated by AR leading to prostate cancer progression." (PMID 35317831, 2022). "In addition to de novo resistance, patients who receive second-generation AR antagonists inevitably develop acquired resistance within a variable period of time, which represents the greatest challenge of AR antagonists in prostate cancer treatment." (PMID 35864113, 2022). "Moreover, interplay among DNA methylation, cancer metabolism and androgen receptor regulation has been reported to play an important role in prostate cancer." (PMID 36095024, 2022). "Moreover, dysregulated AR activity is a driving force in prostate cancer (PCa) initiation and progression." (PMID 35723327, 2022). "The androgen receptor (AR) plays a key role in the mechanism of prostate carcinogenesis, and it exerts an important influence on prostate cancer cell proliferation, survival, and differentiation, mainly by regulating the androgen-induced different gene expression program." (PMID 36008934, 2022). "This suggests that metformin may use both AR-dependent and AR-independent pathways to regulate prostate cancer proliferation." (PMID 36175875, 2022). "We investigated whether bicalutamide in combination with SPH would mitigate the rate of colony formation in AR-positive LNCaP prostate cancer cells in a synergistic manner." (PMID 35447901, 2022). "For treatment of prostate cancer suppression of androgen receptor (AR) function is important." (PMID 35954308, 2022). "It is also a target gene of AR and has responsive effects to androgen in prostate cancer cells." (PMID 36262352, 2022).
prostate carcinoma (continued). "In prostate cancer cells, for example, the cytosine-rich domain of antisense AR-eRNA, which is predicted to form a stem-loop structure, is key for AR-eRNA function, recruiting DNA methyltransferase 1 (DNMT1) to the associated enhancer to alter the DNA methylation levels of AR target loci." (PMID 36039999, 2022). "Furthermore, we investigated the mechanism of AR inhibition and the antiandrogenic effects of these PFASs on the expression of androgen responsive genes and intracellular AR protein levels in androgen sensitive human prostate cancer cells." (PMID 35093747, 2022). "Given that hormone therapy, including ADT and anti-androgens for the last eighty years, has been failed to be a curable approach for metastatic prostate cancers, eliminating the AR protein in prostate cancer cells recently emerged as a realistic solution for a potentially curable result." (PMID 35372068, 2022). "The high occurrence of prostate cancer and the implication of the AR signaling in its growth resulted in the need to find drugs able to sustain most of the anabolic and protein-protective functions of T because of the limited (or counterproductive) benefits of T deprivation." (PMID 36233256, 2022). "As we know, endocrine resistance is a persistent problem in advanced prostate cancer that may be mediated by androgen receptor (AR)-V7." (PMID 35359945, 2022). "Taken together, these results highlight a complex relationship between fibroblast AR expression and prostate cancer growth, and emphasize the need for further work exploring the functional importance of stromal AR during prostate cancer and its predictive value." (PMID 36671452, 2022). "Research has demonstrated that PLK1 could affect androgen receptor elevation, lipid metabolism, and response to androgen signaling inhibitors in prostate cancer by regulating the PI3K/AKT signaling pathway." (PMID 36439881, 2022). "Therefore, in prostate cancers with the TMPRSS2-ERG fusion oncogene, activation of AR signaling upregulates the expression of this fusion oncoprotein, leading to enhanced proliferation and survival and prostate cancer cells." (PMID 35960413, 2022). "Enzalutamide or MDV-3100 (IUPAC name: 4-(3-(4-cyano-3-(trifluoromethyl)phenyl)-5,5-dimethyl-4-oxo-2-thioxoimidazolidin-1-yl)-2-fluoro-N-methylbenzamide) is a potent AR signaling inhibitor approved to treat patients with metastatic castration-resistant prostate cancer." (PMID 36548336, 2022). "Notably, AR+FOXA1+ prostate cancer cells were more sensitive to these inhibitors than SMARCA4-null cancer cell lines." (PMID 34937944, 2022). "Interestingly, the R1881 treatment only partially reversed ivermectin-mediated cell apoptosis and DNA damage, suggesting that there was an AR-independent pathway for the effect of ivermectin in prostate cancer." (PMID 36050295, 2022). "SIAH2 may interact with estrogen signaling in breast cancer cells in an analogous manner to AR in prostate cancer cells." (PMID 35789210, 2022). "The androgen receptor (AR) is a central driver of aggressive prostate cancer." (PMID 35087237, 2022). "Further to this, AR expression in macrophages has been reported to aid in prostate cancer invasion." (PMID 37435460, 2022). "Downregulation of USP14 may suppress cell proliferation, migration, and promote cell apoptosis via stabilizing AR in prostate cancer or AR-positive BCa." (PMID 36423684, 2022). "In addition to that of HP1β, knockdown of HP1γ downregulates AR expression and the proliferation of prostate cancer." (PMID 35159030, 2022).
prostate carcinoma (continued). "In vivo experiments using subcutaneous prostate cancer xenografts indicated that iRGD-modified liposomes significantly enhanced the antisense oligonucleotide against androgen receptor accumulation and reduced the androgen receptor expression in prostate tumors." (PMID 35456655, 2022). "Since metformin suppresses AR expression within advanced prostate cancer cells, it may serve as an effective way to control AR signaling in drug-resistant cancers." (PMID 36175875, 2022). "Overall, these findings suggest that ivermectin could block NHEJ repair by targeting Ku70/Ku80 and HR repair by downregulating the expression of BRCA1 and Rad51, thereby triggering synthetic lethality in AR-positive prostate cancer cells." (PMID 36050295, 2022). "Prostate cancer also utilizes similar mechanisms to overcome androgen- and AR target therapies." (PMID 35774123, 2022). "One well-known example is the androgen receptor (AR) isoforms in prostate cancer (PrCa)." (PMID 36293264, 2022). "By contrast, the epigenomic landscape of prostate cancer appears to undergo highly recurrent alterations—in particular, alterations to chromatin binding patterns of transcriptional regulators such as the androgen receptor (AR)." (PMID 35509021, 2022). "In addition, PROTAC 43 potently induced caspase activation and apoptosis in prostate cancer cells compared to AR inhibitors." (PMID 36142231, 2022). "It is thus tempting to speculate that MYC decreases the reliance of prostate cancer cells on the canonical AR transcriptional program, therefore facilitating resistance to AR-targeted therapies." (PMID 35562350, 2022). "However, more research is needed to better characterize the relationship between the mechanical aspect of matrix stiffness and the molecular features of prostate cancer, especially with regards to AR signaling." (PMID 35740556, 2022). "Curcumin can inhibit lung cell proliferation, inhibit prostate cancer cell growth via inhibition of androgen receptor pathways, inhibit prostate cancer bone metastasis, and inhibit epithelial mesenchymal transition and invasion induced by cancer-associated fibroblasts in prostate cells." (PMID 36497414, 2022). "Previously, it was shown that KDM4B interaction with AR signaling occurs in prostate cancer." (PMID 35317831, 2022). "Furthermore, TR3 overexpression increased cell proliferation and mobility of AR-positive prostate cancer cells and stimulated tumorigenesis of androgen-independent prostate cancer cells in mouse xenograft models." (PMID 35454821, 2022). "Accordingly, it has been reported that FOXH1 can act as a hormone-independent corepressor of AR in prostate cancer cells; indeed, a protein-protein interaction was identified between the AR AF-1 domain and FOXH1 independently of the presence of dihydrotestosterone." (PMID 36407312, 2022). "In addition, ELK1 directly bind to AR to upregulate a major subset of its target genes which is essential to prostate cancer cell growth and survival." (PMID 36439881, 2022). "In addition, HSP90 can also regulate the proliferation and apoptosis of prostate cancer cells through AR, ERBB2, Akt, c-RAF, survivin, EGFR, IGFR-1, STAT3, ERK, CDK-4, and CDK-6 signaling pathways." (PMID 36294924, 2022). "Although the precise timelines of these molecular events may be challenging to dissect, recognizing the alterations to the epigenome and the AR cistrome that accompany disease progression can point to vulnerabilities in prostate cancer." (PMID 36212399, 2022).
prostate carcinoma (continued). "Furthermore, PROTAC 8 reduced AR levels in prostate cancer-resistant cells LNCaP (approximately 3.5-fold at 10 μM), while AR was substantially increased in cells treated with enzalutamide (approximately 17.5-fold at 10 μM)." (PMID 35702041, 2022). "Altogether, this suggests that combined blockade of AR and NF-κB might be beneficial for treatment of metastasizing prostate cancer." (PMID 36551650, 2022). "They further demonstrated that SIRT7 expression is positively correlated with AR signaling in both prostate cancer tissues and cells (LNCaP and 22Rv1) and that SIRT7 knockdown upregulates SMAD4, a tumor suppressor protein, which interacts with AR to control its signaling in prostate cancer." (PMID 36291902, 2022). "Thus, the factors surrounding these classes of sites appear to be distinct and potentially impact the unique transcriptomic profiles of AR specific isoforms in prostate cancer models." (PMID 35354884, 2022). "However, in the process to advance prostate cancer, not only AR but also androgen metabolism changed." (PMID 36362304, 2022). "Prostate cancer (PCa) progression depends on androgen receptor (AR) activity." (PMID 35111229, 2022). "The AR signaling pathway is active during prostate cancer progression." (PMID 35168543, 2022). "Indeed, numerous evidences support a reciprocal cross talk between AR and IGF signaling that enhances AR transactivation and prostate cancer growth." (PMID 36140255, 2022). "In addition, SNRPE was found to be involved in cell proliferation and the progression of prostate cancer by regulating androgen receptor mRNA expression in cells." (PMID 36371223, 2022). "Mutations of the androgen receptor (AR) are associated with the development of prostate cancer (PCa) by responding to non-androgenic hormones, and the lack of annotations in their responsiveness to hormone ligands remains a daunting challenge." (PMID 36459502, 2022). "To strengthen our hypothesis, we further investigated the profile of transcription repression by full‐length AR in available RNA‐seq datasets from prostate cancer cells." (PMID 34919781, 2022). "Furthermore, in prostate cancer cells, miR-133a-5p reduces cellular invasiveness and proliferation via targeting the androgen receptor (AR)." (PMID 35966888, 2022). "An increasing number of studies have investigated the clinicopathology and molecular character of prostate cancer with neuroendocrine differentiation in the past years, but the understanding of AR status in prostate cancer neuroendocrine differentiation progression remains controversial." (PMID 36033483, 2022). "Androgen receptor (AR) is the essential driver and therapeutic target in prostate cancer." (PMID 35707002, 2022). "Targeting the AR signaling axis is the mainstay of prostate cancer therapy." (PMID 36050295, 2022). "Moreover, one of the most frequently mutated E3 ubiquitin ligases in prostate cancer, SPOP, reportedly promotes ubiquitination-mediated proteasomal degradation of AR." (PMID 35203681, 2022). "This may be due to the fact that different types of prostate cancer are diverse in AhR and AR receptor content, and subcellular localization, and that AhR presence may affect AR phosphorylation status." (PMID 36613955, 2022). "This indicates that prostate cancer treatment may benefit from combining AR antagonist therapy with inhibitors targeting the AR co-factors that facilitate antagonist-induced reprogramming of AR transcriptional activity." (PMID 35864113, 2022). "AR contributes to the upregulation of key genes for prostate cancer progression." (PMID 34919781, 2022). "In addition, TLE5 inhibits the metastasis of colorectal cancer and prostate cancer by inhibiting the Notch and androgen receptor (AR) signaling pathways." (PMID 36438567, 2022).